NFKB1 (nuclear factor kappa B subunit 1)
Diseases named in the same sentence as NFKB1 in open-access papers (continued):
Sharing a sentence is not in itself a finding about the gene and the disease.
adenoma (39 papers, 2009 to 2025). A neoplasm arising from the epithelium. "ABCB1 C-rs3789243-T and NFKB1 -94ins/del homozygous variant genotypes were associated with lowered ABCB1 mRNA levels in morphologically normal tissue from adenoma cases." (PMID 23977225, 2013). "The ABCB1 C-rs3789243-T and NFKB1 -94ins/del homozygous variant genotypes were associated with low ABCB1 mRNA levels in morphologically normal sigmoid tissue from adenoma cases (P<0.05 for both)." (PMID 23977225, 2013). "In contrast, ABCB1 mRNA levels in the carcinogenic tissue and the morphologically normal tissue surrounding the tumour are lowered independently of the studied polymorphisms in ABCB1 and NFKB1 suggesting any regulation by these polymorphisms is lost once adenomas have been formed." (PMID 23977225, 2013). "Adenomas from wild‐type mice had an apoptotic index of 7.6 ± 2.6 cells per hpf, which was similar in Nfkb1−/− and c‐Rel−/− mice." (PMID 25727407, 2015). "Adenomas from wild‐type mice had a mean Ki67+ proliferating cell index of 297 ± 20.4 cells per high power field (hpf); adenomas examined from Nfkb1−/− and Nfkb2−/− mice had similar proliferative indices." (PMID 25727407, 2015). "In the present study our aim was to assess the intestinal levels of ABCB1 and NFKB1 mRNA in adenoma and CRC cases and in control subjects in order to characterize the role of ABCB1 in the development of CRC." (PMID 23977225, 2013).
autism (38 papers, 2011 to 2025). Persistent deficits in social interaction and communication and interaction as well as a markedly restricted repertoire of activity and interest as well as repetitive patterns of behavior. "In addition, gastrointestinal dysfunction symptoms associated with autism include NFKB1 as a biomarker." (PMID 33374967, 2020).
migraine (38 papers, 2013 to 2026). "Of note, 4q24 (chromosome 4: 103,388,441–104,802,530), with the strongest local effect, harbors gene NFKB1 encoding the subunits of nuclear factor‐κB (NF‐κB) transcription factor, known to associate with migraine, kidney function, and CKD." (PMID 37306871, 2023).
infarction (37 papers, 2009 to 2026). A localised pathological necrosis of tissue resulting from obstruction of the blood supply usually by a thrombus, an embolus, or vascular torsion. "NFKB1 upregulation started at the early phases of myocardial IRI, and its expression was maintained up to 28 days post-infarction." (PMID 35621843, 2022).
ovarian tumor (35 papers, 2012 to 2025). "In contrast, miR-9 is downregulated in human ovarian tumor cells and overexpression of miR-9 suppresses their proliferation, in part by downregulating NFκB1." (PMID 24517413, 2014). "Conversely, miR-9 has been shown to target and repress NFκB1 translation in ovarian tumor cells by binding to the 3′ untranslated region (3′ UTR) of the NFκB1 mRNA, leading to inhibition of cell proliferation; hence demonstrating a tumor suppressor function." (PMID 24373626, 2013).
brain inflammation (33 papers, 2011 to 2025). "Since deletion of Nfkb1 can decrease the inflammatory response to brain injury and age-related brain inflammation is linked to augmented Nfkb1 expression, it is possible that the enhanced expression of Nkfb1 plays a role in the persistent inflammation observed in the hippocampus of GWI-rats." (PMID 28659758, 2017).
common variable immunodeficiency (33 papers, 2016 to 2026). "Heterozygous loss‐of‐function pathogenic variants in NFKB1 are the most common monogenic cause of common variable immunodeficiency (CVID), presenting with hypogammaglobulinemia, recurrent respiratory infections and reduced switched memory B cells." (PMID 41532450, 2026). "A notable example is NFKB1 haploinsufficiency, now recognized as the most frequent monogenic cause of common variable immunodeficiency (CVID)." (PMID 40909287, 2025). "Recently, heterozygous loss-of-function NFKB1 variants were identified as the primary cause of common variable immunodeficiency (CVID) in the European population." (PMID 38514645, 2024). "The gene most frequently affected (57 afflicted persons, 13.5 %) is the NFkB1 gene associated with common variable immunodeficiency (CVID)." (PMID 38235015, 2023). "Whole exome sequencing confirmed a previously reported pathogenic variant in the NFKB1 gene linked to common variable immunodeficiency 12 (CVID-12) diagnosis for both patients." (PMID 38130541, 2023). "Heterozygous pathogenic sequence variants in NFKB1 have been identified as the most frequent monogenic cause in common variable immunodeficiency (CVID)-like diseases." (PMID 36105815, 2022). "Heterozygous mutations in NFKB1 encoding the precursor p105 results in p50 haploinsufficiency which appears to be the most common cause of Mendelian common variable immunodeficiency (CVID)." (PMID 36733767, 2022). "Also very interestingly, recent work highlighted, at least in part, why sexual dimorphisms exists in patients with variants in NFKB1 causing common variable immunodeficiency (CVID)." (PMID 41608500, 2025). "Most commonly, NFKB1 loss-of-function (LOF) causes B cell deficiency in individuals suffering from common variable immunodeficiency (CVID)." (PMID 36892687, 2023). "In common variable immunodeficiency (CVID), heterozygous damaging NFKB1 variants represent the most frequent monogenic cause." (PMID 33995346, 2021). "Mutations in the NFκB1 pathway are associated with primary immune defects and underlie the most common monogenic etiology of common variable immunodeficiency (CVID)." (PMID 34307247, 2021). "Common variable immunodeficiency-12 (CVID12) is an autosomal dominant subtype of CVID, resulting from genetic mutations of NFKB1." (PMID 41148944, 2025). "Common variable immunodeficiency-12 (CVID12), an autosomal dominant subtype of CVID, is an immune condition resulting from loss-of-function mutations of NFKB1." (PMID 41226891, 2025). "This analysis revealed a significant similarity of the NFKB1-/- transcriptional signature with “Severe combined immunodeficiency” and “Common variable immunodeficiency” disease signatures." (PMID 34721373, 2021). "NFKB2 was first reported as the gene responsible for autosomal dominant (AD) common variable immunodeficiency (CVID) (OMIM: 615577), and this discovery was followed by NFKB1 as another gene responsible for AD-CVID." (PMID 33499153, 2021).
alcohol (32 papers, 2007 to 2025). "Confirmation of candidate genes in the Nfkb1 pathway, which is associated with alcohol dependence, is ongoing." (PMID 20128895, 2010). "Furthermore, in a human genome–wide association study, eight SNPs across the NFKB1 gene showed significant association with alcohol dependence and in mice, alcohol consumption was reduced by I-κB kinase inhibition (an activator of NF-κB activity;)." (PMID 37296629, 2023). "In fact, NF-κB DNA binding in the brain has been shown to increase with ethanol treatment and the human NFKB1 gene has also been linked with alcoholism." (PMID 27822501, 2016).
gastric adenocarcinoma (27 papers, 2007 to 2025). "Positive immunoreactivity was observed in 51 (51 %) and 58 (58 %) gastric adenocarcinomas for NFKB1 and RELA staining respectively." (PMID 26801246, 2016). "The findings revealed that the expression of NFKB1 and HIF1A genes was significantly high, and IL-6 expressed the same between the stomach adenocarcinoma tissues compared to normal tissues." (PMID 39816318, 2024). "We have recently shown that mice lacking NF-κB1 (Nfkb1-/-), a member of the canonical NF-κB signaling pathway develop inflammation-driven invasive gastric adenocarcinoma." (PMID 35844493, 2022). "The study analysed the mRNA expression levels of ALB, BCL-2, NFKB1, HIF1A, and IL-6 in 408 stomach adenocarcinoma samples alongside non-tumour gastric tissues." (PMID 39816318, 2024).
Sjögren’s syndrome (26 papers, 2011 to 2025). "Our analysis revealed that only one clinical trial had evaluated the drug thalidomide targeting NFKB1 for Sjögren’s Syndrome (NCT00001599)." (PMID 35268532, 2022). "No clinical trials were found to evaluate drugs with EGFR as a target and only one clinical trial has evaluated a drug with NFKB1 as a target for Sjögren’s Syndrome (NCT00001599)." (PMID 35268532, 2022).
ZIKV infection (26 papers, 2018 to 2026).
necrotizing enterocolitis (25 papers, 2011 to 2025). Necrotizing enterocolitis (NEC) is a devastating disease that affects mostly the intestine of premature infants. "Among the genetic alterations associated with necrotizing enterocolitis, the -94ins/delATTG polymorphism in NFKB1 gene leads to unregulated activation of the NFKB protein due to an increase in the inherent pro-inflammatory state of the premature intestine." (PMID 36629694, 2023). "The absence of the -94ins/delATTG polymorphism in NFKB1 gene in newborns with and without necrotizing enterocolitis does not rule out the possibility of alterations in this and/or in other genes in newborns with this condition, which reinforces the need for further research." (PMID 36629694, 2023).
T-cell leukemia (25 papers, 2005 to 2025). A malignant disease of the T-lymphocytes in the bone marrow, thymus, and/or blood. "EμSRα-TEL-JAK2;Nfkb1−/− and EμSRα-TEL-JAK2;Nfkb1+/− littermate mice developed T-cell leukemia with full penetrance and similar latency (median survival of 12 weeks)." (PMID 18596915, 2008).
Huntington disease (23 papers, 2011 to 2026). Huntington disease (HD) is a rare neurodegenerative disorder of the central nervous system characterized by unwanted choreatic movements, behavioral and psychiatric disturbances and dementia. "In particular, Huntington’s disease signaling, T cell activation, Apoptosis and survival signaling were the most significantly enriched pathways in both SALS patient subgroups, with AKT1, NFKB1 and SOS as the major key involved genes." (PMID 31292500, 2019).
liver cirrhosis (22 papers, 2017 to 2026). "1.SP1, RELA, and NFKB1 were identified as key regulators in regulating the liver cirrhosis process." (PMID 41586310, 2025).
Splenomegaly (22 papers, 2014 to 2025). Abnormal increased size of the spleen. "The two remaining patients with a deleterious NFKB1 missense variant had splenomegaly and autoimmune cytopenias as common features and started at a young age with the first symptoms (1.5 and 12 years, respectively)." (PMID 36105815, 2022). "An NFKB1 variant was found in a patient with recurrent autoimmune hemolytic anemia, antibody deficiency and splenomegaly and a TRAF3 variant was found in a patient with antibody deficiency." (PMID 34992599, 2021). "Macrophage neoplasm in Nfkb1-/-/Tax+ mice is a systemic malignancy that seems originally derived from adrenal glands, as adrenomegaly occurs earlier than lymphadenopathy and splenomegaly in the mice." (PMID 38722890, 2024).
antibody deficiency (20 papers, 2014 to 2025). "Pathogenic NFKB1 variants are associated with highly variable disease phenotypes, among which antibody deficiency, hyperinflammatory lesions, and autoimmune phenomena are the most frequent manifestations, with a very variable age of onset of symptoms." (PMID 36105815, 2022). "Most patients with damaging NFKB1 mutations have typical CVID manifestations such as hypogammaglobulinemia, low switched memory B cells, respiratory and less frequent gastrointestinal infections." (PMID 33995346, 2021). "Several independent studies have reported that loss-of-function variants in NFKB1 are probably the common cause of antibody deficiency with a highly variable clinical and immunological presentation." (PMID 35003082, 2021). "In this study, we have analyzed targeted gene panel sequencing results of 270 patients diagnosed with antibody deficiency and identified five disease-associated variants in NFKB1 in five unrelated families." (PMID 31803180, 2019). "We analyzed 270 patients with antibody deficiency and identified five monoallelic mutations in NFKB1 in nine subjects." (PMID 31803180, 2019). "Among all tested genes, NFKB1 alterations were the most common monoallelic cause of antibody deficiency in our cohort." (PMID 31803180, 2019). "Overall, monoallelic mutations in NFKB1 have been shown to impose B-cell dysfunction including immunoglobulin and antibody deficiencies often accompanied by autoimmune and also autoinflammatory responses." (PMID 29403474, 2017). "We identified further a previously uncharacterized NFKB1 missense variant in a family with a history of meningococcal meningitis and late-onset hypogammaglobulinemia by next-generation sequencing (NGS) as the only predicted deleterious variant within genes of inborn errors of immunity." (PMID 35003082, 2021). "For instance, mutations in TNFRSF13B, NFKB1, NFKB2, CTLA4 and STAT3 are indications for the early molecular diagnosis of patients with predominantly antibody deficiency such as predominantly antibody deficiencies." (PMID 37033178, 2023). "Within the IEI classified as predominant antibody deficiency, we detected specific IgG+ RBD+ MBCs in half of them, with the exception of 1 patient with CVID, 1 patient with NFKB1 deficiency, 1 patient with NFKB2 deficiency, and 1 patient with suspected IEI without confirmed genetic diagnosis." (PMID 37215146, 2023). "A number of previous studies have outlined the clinical phenotypes of large patient groups with antibody deficiency who have mutations in selected genes, including the TACI gene, CTLA4, NFKB1, NFKB2, STAT3, PI3KCD, or LRBA." (PMID 38274105, 2023). "The NFKB1 variants, which showed only a minor functional defect or for which no defect could be specified, were identified in patients with CVID (n=11), antibody deficiency (n=6), autoinflammatory disorder (n=2), CID (n=1) or in unaffected individuals (n=4)." (PMID 36105815, 2022). "Heterozygous pathogenic variants in NFKB1 and NFKB2, the genes encoding the central components of the canonical and non-canonical NF-κB signaling pathways, have both been associated with primary antibody deficiencies." (PMID 33995346, 2021). "We distinguish PIDs such as XLP and STAT3 mutations, which do not typically present with antibody deficiency from disorders such as NFKB1 mutations which, most often present with hypogammaglobulinemia, that are more appropriately termed CVID-like disorders." (PMID 31824486, 2019). "In patients with mild antibody deficiency, it is often difficult to decide when to initiate replacement immunoglobulin therapy; this might be the case for subjects and their family members identified with LOF NFKB1 variants." (PMID 29477724, 2018).
sarcoidosis (20 papers, 2012 to 2025). Sarcoidosis is a multisystemic disorder of unknown cause characterized by the formation of immune granulomas in involved organs. "Several non-HLA susceptibility loci have been described, including IL23R, ATXN2/SH2B3, ANXA11, IL12B, and MANBA/NFKB1.11, 12Functional studies and transcriptome-wide association analyses suggest that these genes participate in key immunologic processes relevant to sarcoidosis." (PMID 41197661, 2025). "Among 19 protein-sarcoidosis associations, strong genetic colocalization evidence was observed for 8 pairs, including BTN3A3, ANXA11, ITPKA, BTN3A1, G3BP1, IL1RN, IL2RB, and NFKB1." (PMID 40075078, 2025). "Additionally, the miRNet tool showed three transcription factors (PPARG, NFKB1, and RELA) exhibited the highest levels of interaction with the common DEGs shared between sarcoidosis and LC." (PMID 40797277, 2025). "In addition, several genetic variants within or near non-HLA genes were also significantly associated with sarcoidosis: BTNL2, PTGS2/COX2, and PACERR (PTGS2 Antisense NFKB1 Complex-Mediated Expression Regulator RNA)." (PMID 31126090, 2019).
Epstein-Barr virus infection (19 papers, 2020 to 2025). An infection that is caused by Epstein-Barr virus. "We found one pathogenic variant in the NFKB1 gene in a father and his daughter, one pathogenic variant in the TNFRSF13B gene, and one pathogenic variant in the MAGT1 gene associated with X-linked immunodeficiency with magnesium defect, Epstein-Barr virus infection, and neoplasia (XMEN syndrome)." (PMID 38406025, 2024).
insomnia (19 papers, 2017 to 2026). A sleep disorder characterized by difficulty in falling asleep and/or remaining asleep. "A transcription factor (TF)–target analysis of the TRRUST database reveals that numerous targets are regulated by TFs such as NFKB1, RELA, SP1, JUN, and others, suggesting that these TFs may play an important role in insomnia." (PMID 38927034, 2024).
intracranial aneurysms (19 papers, 2016 to 2026). "Authors of a case-control study suggested that the NFKB1 -94ins/del ATTG polymorphism might contribute to the risk of intracranial aneurysms." (PMID 26830841, 2016). "Specifically, intracranial aneurysms with larger size and size ratio exhibit increased expression of CD68 and NFKB1, which reflect acute inflammation and the activation of inflammatory pathways, respectively." (PMID 41368358, 2025).
rectal cancer (19 papers, 2010 to 2025). A primary or metastatic malignant neoplasm that affects the rectum. "Conversely, in rectal cancer, only NFKB1 SNPs were independently associated, with 3 of 4 polymorphisms increasing risk." (PMID 21129206, 2010). "Our findings suggest that polymorphisms in IKBKB, IL6, and NFKB1 may jointly interact to influence colon and rectal cancer risk through an inflammation-related pathway." (PMID 21129206, 2010). "In conclusion, hapConstructor provided a useful tool to systematically and comprehensively guide our exploration of multilocus SNP combinations in three candidate inflammation-related genes, IKBKB, IL6, and NFKB1 in a U.S. case-control study of colon and rectal cancer." (PMID 21129206, 2010). "The combination of ASCC3 with several immune-related genes, including JAK1, NFKB1, SEMA5A, NR2C2, CNTF and CREB1, plays a significant predictive role in the prognosis of rectal cancer patients." (PMID 40881169, 2025). "In rectal cancer, only two-locus composite genotypes across IKBKB and NFKB1, and IL6 and NFKB1 markers met significance thresholds." (PMID 21129206, 2010). "Additionally, our diagnostic and prognostic models, constructed using machine learning, highlight the significant predictive value of ASCC3 in combination with various immune-related genes, including JAK1, NFKB1, SEMA5A, NR2C2, CNTF and CREB1, for rectal cancer prognosis." (PMID 40881169, 2025).
tauopathy (19 papers, 2021 to 2026). Neurodegenerative disorders involving deposition of abnormal tau protein isoforms (tau proteins) in neurons and glial cells in the brain. "In contrast, MG2 and MG4, disease-associated cells induced by tauopathy, exhibit higher levels of proinflammatory genes like Apoe, Spp1, Nfkb1, and Akt3, as well as STAT3, IL-8, NF-kB, and JAK/STAT signaling." (PMID 37961627, 2023).
Infertility (18 papers, 2013 to 2025). "We hypothesized that NFKB1 variants and its regulator pre-mir-146a and the possible failures of sperm membrane-associated proteins such as E-cadherin could be potentially involved in the pathogenesis of infertility of oligospermia." (PMID 29942932, 2018).
Shock (18 papers, 2008 to 2025). The state in which profound and widespread reduction of effective tissue perfusion leads first to reversible, and then if prolonged, to irreversible cellular injury. "This is of particular interest as other genetic variants, i.e. the NFKB1 promoter polymorphism -94ins/delATTG, turned out to be an independent predictor for 30-day mortality from septic shock, in a similar patients cohort of 143 patients." (PMID 27515179, 2016).